RGPD1 (RANBP2 like and GRIP domain containing 1)
Synonyms: RanBP2L6; RGP1; RanBP2L2
Gene: Protein-coding gene on chromosome 2 (86,913,783 to 87,013,976, forward strand). Ensembl gene ENSG00000187627.
Subcellular location (Human Protein Atlas): Nuclear membrane; Vesicles
Genetic constraint (gnomAD): Loss-of-function variants: 7 observed, 8.94 expected, observed/expected ratio (o/e) 0.78, 90% interval 0.44 to 1.46. That is too few expected variants to judge how well the gene tolerates losing a copy. Missense variants: 46 observed, 95.8 expected, observed/expected ratio (o/e) 0.48, 90% interval 0.38 to 0.61. Synonymous variants: 20 observed, 35.39 expected, observed/expected ratio (o/e) 0.57, 90% interval 0.4 to 0.82.
Homologues: Orthologues: zebrafish ranbp3a (5% identical), Drosophila melanogaster RanBP3 (5% identical). Paralogues in human: RGPD2 (99% identical), RGPD4 (96% identical), RGPD3 (95% identical), RGPD5 (93% identical), RGPD6 (93% identical), RGPD8 (93% identical), RANBP2 (83% identical), RANBP3 (7% identical), RANBP3L (4% identical), RANBP1 (4% identical).
Diseases named in the same sentence as RGPD1 in open-access papers:
RGPD1 is named in the same sentence as 2 diseases in open-access papers, as found by Europe PMC text mining. Sharing a sentence is not in itself a finding about the gene and the disease. The quoted sentences say what the papers report.
folate deficiency (1 paper, 2025). A nutritional condition produced by a deficiency of FOLIC ACID in the diet. "RGPD1 is involved in import of nuclear localisation signal bearing proteins into the nucleus and linked to cerebral folate deficiency, which may be relevant to the patient phenotype of athetoid cerebral palsy." (PMID 41023835, 2025).
RGPD1 also shares sentences with these, for which no sentence is quoted: cancer (1 paper).